RNU6-262P (RNA, U6 small nuclear 262, pseudogene)
Gene: Small nuclear RNA gene on chromosome 11 (119,289,562 to 119,289,677, reverse strand). Ensembl gene ENSG00000222249.
Homologues: Orthologues: chimpanzee U6 (99% identical), macaque U6 (78% identical), dog U6 (76% identical), guinea pig U6 (72% identical), dog U6 (71% identical), guinea pig U6 (70% identical), dog U6 (69% identical), guinea pig U6 (69% identical), pig U6 (69% identical), dog U6 (67% identical), rat LOC120103227 (63% identical). Paralogues in human: RNU6-31P (80% identical), RNU6-949P (79% identical), RNU6-1011P (78% identical), RNU6-11P (78% identical), RNU6-12P (78% identical), RNU6-132P (78% identical), RNU6-13P (78% identical), RNU6-24P (78% identical), RNU6-26P (78% identical), RNU6-32P (78% identical), RNU6-33P (78% identical), RNU6-37P (78% identical), and 1281 more.